IL18 (interleukin 18)
Diseases named in the same sentence as IL18 in open-access papers (continued):
Sharing a sentence is not in itself a finding about the gene and the disease.
tumor (continued). "Peripheral blood NK cells can be briefly activated with IL-12, IL-15 and IL-18 to induce differentiation into memory-like NK cells, associated with enhanced responses when simulated through tumor targets for weeks to months after pre-activation." (PMID 37207215, 2023). "After the NLRP3 inflammasome is activated, it cannot produce self-inhibition even in a resting state, which results in the continuous production of IL-1β and IL-18, finally causing long-term effects on inflammation and tumor diseases." (PMID 35292015, 2022). "The activation of hypoxia signaling increases the expression of adipokines, especially the pro-inflammation adipokines (including CCL2, CXCL8, CXCL10, IL-18, IL-1α and Oncostatin M), which is involved in the recruitment of tumor-associated immune cells." (PMID 35350384, 2022). "We demonstrate by staining serial sections that IL18 was mainly expressed by M1-like (CD68+/CD163-) tumor-associated macrophages (TAM) but also M2-like (CD68+/CD163+) TAMs in our cohort." (PMID 36131941, 2022). "Herein, drug sensitivity assessment demonstrated that IL18 expression was negatively linked to some or most drugs in the tumor therapeutic response Portal database." (PMID 35785176, 2022). "Th1 cytokines, such as IL‐1β, IL‐2, IL‐12, IL‐18, TNFα, and IFNγ, are associated with proinflammation, while Th2 cytokines, such as IL‐4, IL‐5, and TGFβ, play a suppressive role in the tumour immune microenvironment." (PMID 35430766, 2022). "A high level of IL-18 was found to be associated with angiogenesis, tumor cell migration, and metastasis." (PMID 36237303, 2022). "IL-18 is secreted from tumor-associated macrophages (TAMs) and stimulates tumor growth, similar to IL-6." (PMID 35892729, 2022). "This antibody alone attenuates tumor growth, and when combined with the PD-1 antibody, it further slows tumor progression; 50% of mice show complete tumor rejection via a mechanism associated with P2RX7/NLRP3/IL-18 activation in myeloid cells." (PMID 35454832, 2022). "GM-CSF production seems to have a synergistic effect with Toll-Like Receptor—2 (TLR2) to inhibit tumor growth and modulate tumor-infiltrating Antigen Presenting Cells (APCs), and IL-18 has been associated with better survival rates in cancer patients." (PMID 36296703, 2022). "Anti-human MARCO (anti-hMARCO) antibody targeting triggered the repolarization of tumor-associated macrophages and activated the inflammasome machinery, resulting in IL-18 production." (PMID 36310582, 2022). "Conversely, the markedly reduced IL-18 expression in NLRP3-deficient mice results in dramatically increased tumour burden in the colon." (PMID 33918087, 2021). "It was also observed that tumor-associated neutrophils are involved in regulating tumor development, while IL-1β and IL-18 route neutrophils to tumor sites." (PMID 34837692, 2021). "High expression of IL-18 has been detected in various cancers, and tumor-derived IL-18 is associated with a poor prognosis." (PMID 33718235, 2021). "There was a statistically significant association between tumor size and different genotypes of IL18 genes, where 62.5% of patients with tumor size >5 cm carried the risky (AA) genotype." (PMID 33773554, 2021). "In NPC, the elevated levels of IL-18 in cancer cells were associated with a high density of tumor infiltrating NK cells and poor overall rates of survival." (PMID 33718235, 2021). "In line with this notion, the dysregulation of inflammasome signaling and/or consequent reduction of IL-1β and IL-18 production were associated with tumor growth and metastasis in colorectal cancer." (PMID 34490126, 2021). "Better tumour surveillance of probiotic-fed DMH rats can be also linked to this probiotic potential to induce IL-18 secretion, as IL-18 is critically involved in protection against colorectal tumorigenesis." (PMID 32168834, 2020).
tumor (continued). "In some cases, high levels of IL-18 have been associated with advanced tumor stage or poor prognosis, suggesting a pro-tumorigenic role for IL-18." (PMID 33261061, 2020). "In different murine cancer models, the association of blocking Abs against CD39 and PD-1 slows tumor growth through a NLRP3/IL-18-dependent and IL-1β-independent mechanism." (PMID 33261061, 2020). "Inactivation of NLRP3 inflammasome driven by miR-233-3p has been found to decrease the expression of NLRP3 inflammasome-associated proteins, ASC, IL-1β, and IL-18 in breast cancers and suppress tumor growth." (PMID 33613533, 2020). "IL-1, IL-18, and IL-36, members of the IL-1 family of the cytokines, are pro-inflammatory and mostly associated with tumor growth." (PMID 33718121, 2020). "Inhibition of the NLRP3 inflammasome was seen to reduce tumor burden in the murine model of colitis-associated cancer, with the increased tumor burden correlating with attenuated levels of IL-1β and IL-18 at the tumor site." (PMID 31231372, 2019). "The regulatory mechanisms underlying the maturation and secretion of IL-1β and IL-18 into the tumor microenvironment require profound elucidation." (PMID 31492049, 2019). "Other tumor-promoting effects associated with IL-18 include evasion of the anti-tumor immune response." (PMID 31231372, 2019). "Upstream regulator analysis predicted the increased activation of STAT4, IL-18, and IL-12 pathways in tumor-associated UTCαβ, compared to other T cell subsets." (PMID 31257026, 2019). "The expression of IL‐18 and E‐cadherin was associated with tumor differentiation, whereas the expression of β‐catenin, N‐cadherin, and TNKS2 was associated with tumor de‐differentiation." (PMID 30524946, 2018). "PD-1 expression can be induced by tumour-derived IL-18 on immunosuppressive CD56 (dim) CD16 (dim)/-NK cells, and tumour-derived IL-18 is associated with a bad prognosis in patients with TNBC." (PMID 29848327, 2018). "The expression of IL‐18 and E‐cadherin was associated with tumor differentiation (P < 0.05), whereas the expression of β‐catenin, N‐cadherin, and TNKS2 was associated with tumor de‐differentiation (P < 0.05)." (PMID 30524946, 2018). "In tumor-associated macrophages, leptin induced the expression of IL-18 via NF-kB, possible contributing to tumor progression." (PMID 29910742, 2018). "Elevated expression of IL‐18 (P < 0.01) and E‐cadherin (P = 0.034) was associated with tumor differentiation, whereas expression of TNKS2 (P < 0.01), β‐catenin (P = 0.012), and N‐cadherin (P < 0.01) was associated with tumor de‐differentiation." (PMID 30524946, 2018). "High serum IL-18 levels were significantly associated with poor prognostic factors, such as hormone receptor negativity (p < 0.001), larger tumor size (p = 0.005), nodal involvement (p = 0.021), and a higher Ki67 positivity (p = 0.013)." (PMID 28415798, 2017). "In ovarian cancer, synergistic effect of tumor‐associated IL‐17 and Th17 cells 66, as well as IL‐18‐primed “helper” NK cells 67, induced the production of endogenous CXCL9 and CXCL10 that were directly correlated with tumor‐infiltrating CD8+ T cells." (PMID 27726306, 2016). "The injection of complexed linear DNA encoding interleukin (IL)-12/IL-18 induced partial tumour remission in a clinical study including 27 grey horses." (PMID 26100265, 2015). "The heightened tumor growth in the caspase-1 deficient mice was accompanied with drastically low levels of colonic IL-18." (PMID 25071785, 2014). "Adaptive immune mechanisms were demonstrated to be important in mediating the anti-tumor effects of IL-18, and innate mechanisms are also implicated." (PMID 21935389, 2011). "In other experiments, direct injection of recombinant IL-18 into established tumors also inhibited tumor growth, which was associated with an increase in intratumoral macrophages, but not T cells." (PMID 21935389, 2011).
tumor (continued). "The marked reduction of tumor growth in tumor-bearing mice was associated with the maintenance of IFN-γ production in spleen in response to IL-18." (PMID 17519043, 2007). "Having shown the enhanced activity of the 10,000-fold attenuated IL-18 antibody fusion in vitro, we investigated in vivo anti-tumor activity of three IL-18mut variants fused to a single armed RMP1–14 characterized by attenuations of 100-fold up to 1,000,000-fold." (PMID 41488627, 2025). "Moreover, the activation of purinergic pathways culminates with the production of pro-inflammatory cytokines, such as IL-1β and IL-18, which contribute to an inflammatory microenvironment predisposing to tumor development." (PMID 39456655, 2024). "Besides, leptin increase tumor‐associated macrophages (TAMs), such as increasing IL‐18 which activates the NF‐κB/NF‐κB1 signaling pathway that assist migration and invasion of BC cell." (PMID 38717954, 2024). "In both cases, KCs represented the majority of macrophages in normal liver, but a minor subset in tumoural liver, and expressed higher ID3, lower SIRPA and higher chemokine (CCL4, CCL3) and cytokines genes (IL18) in comparison to CD14+TIM4− tumour-associated macrophages." (PMID 38326607, 2024). "Additionally, the combination of IL-18 and IL-12 would activate T helper (Th) cells and natural killer (NK) cells causing antiviral and anti-tumor immunity." (PMID 36932407, 2023). "Inflammatory cytokines, such as IL-1β and IL-18, and damage-associated molecular patterns (DAMPs) released during pyroptosis can reconfigure the immune microenvironment, activate tumor immunity, or even confer beneficial effects on tumorigenesis and cancer progression." (PMID 37511974, 2023). "Additionally, in a recent study, Mefv (or pyrin)−/− mice were similarly unable to limit the extent of inflammation due to the restricted activation of inflammasomes and IL-18 maturation, resulting in increased tumor susceptibility." (PMID 35733919, 2022). "Various evidence firstly demonstrated that IL-18 is closely associated with tumor growth." (PMID 36237303, 2022). "IL-18 has been implicated in host immune defense against tumor development." (PMID 35159208, 2022). "Low IL18 expression associates with a tumor-to-stroma IL18 gradient away from the stroma (p=0.007)." (PMID 36131941, 2022). "Interestingly, IL-18 is also associated with tumor progression, therefore long-term results concerning the safety of IL-18-expressing CAR-T cells in clinics are highly awaited." (PMID 36389658, 2022). "Moreover, therapeutic bacteria carrying eukaryotic plasmids encoding cytokines such as IL-4 and IL-18, and angiogenesis inhibitors such as endostatin and thrombospondin all resulted in retardation of tumor growth and prolonged survival of tumor-bearing mice." (PMID 36276157, 2022). "Thus, this work demonstrated that KRASG12D mutation suppresses IL-18 chemokine production, possibly contributing to evasion of the local immune system during tumor development." (PMID 35159208, 2022). "We demonstrate for the first time in this study that this cluster is mostly characterized by aCasp1+ tumor cells and production of mature IL-18 associated with the highest level of Tbet+ and PD1+ TILs, possibly resulting in TIL exhaustion, in accordance with the lowest level of IFNγ." (PMID 33430344, 2021). "Taken together, the loss of IL-7, IL-15, and IL-18 may be playing a role in the decreased numbers of lymphocytes in the tumor microenvironment, which supports a protumorigenic environment." (PMID 33290281, 2021). "Interestingly, in 90% of MSI CRCs and 70% of MSS CRCs, an intense IL-18 immunostaining was observed in more than 50% of tumor cells, which was associated with a higher density of intraepithelial CD8+ and Tbet+ TIL (IEL-TIL)." (PMID 33430344, 2021).
tumor (continued). "In mice with HIF1α-deficient NK cells, tumor control was enhanced either directly by increased IL-18 signaling that improved NK cell effector responses or indirectly through an absence of tumor-infiltrating NK cells, which altered the VEGF/VEGFR axis affecting productive angiogenesis." (PMID 34396954, 2021). "Taking into account the association between IL-18 levels in tumor cells and the density of Th1/Tc1 TILs, our working hypothesis is that this “activated functional inflammasome” of tumor cells can facilitate the IFNγ response of TILs in CRC." (PMID 33430344, 2021). "This partial or complete loss of IL-18 protein expression in tumor cells could be accounted for by a decrease or loss of IL-18 transcripts, as suggested by our transcriptional analyses on some CRCs of the prospective cohort and as previously reported." (PMID 33430344, 2021). "Furthermore, it has been shown that inflammasome-deficient mice produced markedly reduced levels of IL-18, which was concomitant with impaired production and activation of tumour suppressor genes IFN-γ and STAT1." (PMID 33918087, 2021). "Furthermore, high expressions of activated inflammasomes, IL-1β and IL-18, are also used as independent predictors of poor prognoses in ccRCC patients, while the tumor promoting cytokine, IL-6, has been implicated in the progression of RCC." (PMID 32714856, 2020). "In that paper, although the authors reported a negative association, they found that the -137 and -607 genotypes of IL-18 were correlated with more advanced stages of RCC, and the genotype related to a higher production of IL-18 was associated with a larger size and T stage of the tumor." (PMID 30925760, 2019). "Indeed, the authors showed that IL-1R8-deficient NK cells in an IL-18-dependent manner were responsible of the anti-metastatic effect in two distinct tumor murine models." (PMID 30939820, 2019). "Together, these studies suggest that targeting IL-18 may represent a potential mechanism to overcome tumor-associated immunosuppression." (PMID 31231372, 2019). "In addition, expression of proteins associated with anti-tumor immunity (eg, IL-12 and IL-18) was increased upon anti–MMP-9 and anti-PDL1 antibody combination treatment." (PMID 30500835, 2018). "Interestingly, the enhanced tumor incidence encountered in Asc−/− mice was associated with a significant attenuation of Il-1β and Il-18 levels in the colon within the tumor tissue." (PMID 29868004, 2018). "However, IL-18 has been shown to accumulate in cancer patients, and increased serum IL-18 levels in cancer patients have been associated with tumor progression and a worse prognosis." (PMID 29599908, 2018). "In addition, administration of recombinant IL-18 in caspase-1 deficient animal models treated with AOM/DSS significantly prevented tumor development." (PMID 30447690, 2018). "Given the potential roles of IL-18 in the immune system against tumor cells, angiogenesis, metastasis, proliferation and immune escape, the IL-18 polymorphisms may modulate the risk of cancer." (PMID 29312552, 2017). "Our data revealed that tumor-derived IL-18 is associated with bad prognosis in patients with TNBC." (PMID 28415798, 2017). "Besides priming of adaptive immunosurveillance, NLRs have been implicated in anti-tumor immunity through the link between IL-18 and increased NK cell activity against tumors." (PMID 24795727, 2014). "Moreover, the expression of human melanoma-associated antigen gp100 and IL-18 from a SIN virus DNA vector induced specific anti-tumor CTL responses and provided anti-tumor protection." (PMID 24937089, 2014). "One possible reason is that carcinogenic mechanism underlying the etiology may differ by different tumor sites and that the -607C/A polymorphisms in IL-18 gene promoter may play a different role in different cancers." (PMID 24130810, 2013).
tumor (continued). "However, novel tumor-specific eQTL are detected for several genes associated with tumor susceptibility, including IL18 (Il18), Granzyme E (Gzme), Sprouty homolog 2 (Spry2), and Mitogen-activated protein kinase kinase 4 (Map2k4)." (PMID 21244661, 2011). "Moreover, Il18, which encodes a proinflammatory cytokine that may enhance anti-tumor ability of natural killer cells against CRC, was among the most downregulated genes following regorafenib treatment, alone or in combination with autogramin-2." (PMID 40772227, 2025). "During pyroptosis, activation of inflammasomes can promote the maturation and release of inflammatory factors such as IL-18, IL-1β, IL-10, etc. which may inhibit antitumor immune effects or cause an inflammatory cascade response, thereby promoting tumor development under particular circumstances." (PMID 35725836, 2022). "However, in this study, we found that the expression of IL18 was significantly decreased in the high-risk group, suggesting that IL18 might act as a tumor suppressor to prevent the progression of BC, which was controversial with previous research." (PMID 35464869, 2022). "In order to verify whether the activation of caspase-1 in tumor cells was associated with secretion of mature IL-18, we assessed the link between the expression of aCasp1 in tumor cells and the levels of mature IL-18 released in culture supernatants of CRC explant cultures." (PMID 33430344, 2021). "In addition, IL-18 expression in tumor cells is associated with the Th1/Tc1 immune microenvironment, suggesting that IL-18 produced by tumor cells could influence the local immune contexture." (PMID 33430344, 2021). "The activation of NK cells suggested that IL-18 may be associated with tumor immune responses." (PMID 33732720, 2021). "IL-18 may confer protection against colitis-associated inflammation and neoplasia by modulating the permeability of the intestinal epithelium, the production of antimicrobial peptides, and the activation levels of the tumor suppressors IFN-γ and STAT1." (PMID 34639191, 2021). "Moreover, the association of anti-IL18 and anti-PD-1 inhibits tumor growth and metastasis in vivo." (PMID 33261061, 2020). "However, IL-18 may participate in promoting tumor angiogenesis, metastasis, and immune escape and thus, there is a risk of tumor progression when using IL-18-expressing CAR T cells in clinical trials." (PMID 32423475, 2020). "Hence, the loss of NLRP6 or IL-18 in epithelial tumor cells was associated to metastatic progression and epithelial expression of inflammasome components had a more important impact on tumor evolution." (PMID 33255437, 2020). "Additionally, leptin has been considered as a mediator of tumor-stromal interactions, where it seems to participate in the crosstalk between breast cancer cells and tumor-associated macrophages M2 by stimulating IL-18 and IL-8 production to promote tumor growth and metastasis." (PMID 31380268, 2019). "Moreover, IL‐18 expression and E‐cadherin expression were associated with OSCC differentiation, whereas N‐cadherin expression was associated with OSCC de‐differentiation, indicating that IL‐18 could inhibit tumor cell EMT." (PMID 30524946, 2018). "Furthermore, IL-33 is considered closely associated with IL-18, which has been demonstrated novelly to be upregulated in cancer patients; thus IL-33 may also highlight a close association with tumor." (PMID 27340318, 2016). "Interleukin-18 improves tumor clearance via direct effects on CAR T cells and indirect actions on cells on a variety of host immune cells, including natural killer, macrophage and dendritic cells." (PMID 41728085, 2026). "With the latest advancements in cancer research related to IL-18, it is necessary to integrate the latest research findings to deepen the understanding of the mechanism of tumor immune escape and promote the improvement of cancer treatment levels." (PMID 41751464, 2026).